AQP4 (aquaporin 4)
Diseases named in the same sentence as AQP4 in open-access papers (continued):
Sharing a sentence is not in itself a finding about the gene and the disease.
optic neuritis (continued). "Historically, patients who manifested symptoms of optic neuritis and acute transverse myelitis were initially diagnosed with NMO via the presence of immunoglobulin G (IgG) against the water channel aquaporin-4 (AQP4 IgG) expressed by astrocytes." (PMID 38903369, 2024). "In anti-AQP4 seronegative patients, anti-myelin oligodendrocyte glycoprotein (MOG) has been detected in patients with optic neuritis and longitudinally extensive transverse myelitis." (PMID 37346048, 2023). "Fourth, the study population included optic neuritis of mixed etiology, such as MS, NMOSD with anti-AQP4 antibody or MOGAD with anti-MOG antibody." (PMID 37104301, 2023). "Although no study has yet to investigate whether AQP4 antibody-positive optic neuritis and depression share a common pathophysiological mechanism, we believe that severe inflammation might be responsible for the high proportion of depression in AQP4 antibody-positive patients." (PMID 37840923, 2023). "Several studies have highlighted differences between anti-AQP4 antibody and anti-MOG antibody-positive optic neuritis." (PMID 37104301, 2023). "We describe here a paediatric AQP4-Ab NMOSD patient who was clinically asymptomatic with normal visual acuity despite swollen optic disc and longitudinally extensive optic neuritis on imaging." (PMID 35332817, 2022). "In this study, the aim is to compare the recovery pattern among patients with acute myelin oligodendrocyte glycoprotein antibody-seropositive optic neuritis (MOG-Ab + ON) attacks and aquaporin-4 antibody-seropositive ON (AQP4-Ab + ON) or -seronegative ON." (PMID 35360549, 2022). "Last, we reported a newly diagnosed AQP4-positive NMOSD (Case 6), in a patient—with a previous history of two optic neuritis- presenting with LETM and brainstem involvement after BNT162b2 second dose." (PMID 36530641, 2022). "MOG-specific antibodies play a central role in the pathogenesis of MOGAD that includes ADEM, anti-aquaporin-4-antibody-seronegative NMOSD, myelitis, and optic neuritis." (PMID 33212299, 2021). "Compared to anti-AQP4 antibody NMOSD, optic neuritis lesions in anti-MOG antibody NMOSD are relatively longer but less likely to reach optic chiasma and are confined in the anterior portion of the optic nerve in MRI." (PMID 34484845, 2021). "Optic neuritis can be seen in LETM of various etiologies, but it is more common in anti-AQP4-positive NMOSD patients." (PMID 33884229, 2021). "Antibodies against MOG are found mostly in patients with optic neuritis (ON), acute disseminated encephalomyelitis (ADEM), and aquaporin-4 antibody (AQP4-abs)-seronegative neuromyelitis optica spectrum disorders (NMOSD)." (PMID 33584514, 2020). "In the early 1990s, more than 10 years before the serum AQP4-IgG and MOG-IgG were measured in patients with ON, a landmark clinical trial of the Optic Neuritis Treatment Trial (ONTT) was performed." (PMID 33013632, 2020). "Therefore, the longitudinally extensive myelitis and optic neuritis lesions observed in patients with NMOSD may be the result of primary astrocytic damage triggered by IgG binding to AQP4, which can activate the immune-system cascade and, in addition, downregulate EAAT2." (PMID 31031597, 2019). "At onset, patients with MOG-Abs are more likely to suffer from simultaneous or rapidly sequential optic neuritis and LETM compared to patients with AQP4-Abs." (PMID 30405519, 2018). "The simultaneous or consecutive occurrence of optic neuritis and myelitis in an HIV-positive patient should alert the clinician to test for the AQP-4 antibody." (PMID 29568625, 2017). "More specifically, a longitudinally extensive optic neuritis (LEON) with chiasma and optic tract involvement was found to be strongly suggestive of AQP4-ON." (PMID 29064441, 2017). "It is characterized by recurrent attacks of optic neuritis, myelitis, and presence of NMO-immunoglobulin G (NMO-IgG)/aquaporin-4 antibodies (AQP4-Ab)." (PMID 26989546, 2016).
optic neuritis (continued). "Another AQP4-autoimmunity disease, NMO-spectrum disorder (NMOSD), classifies, not only optic neuritis and myelitis as NMO, but also cerebral, diencephalic, brainstem, and area postrema syndromes." (PMID 27517922, 2016). "Its relapsing nature was noted in the 20th century while the discovery of highly-specific anti-aquaporin-4 (AQP4) antibodies established NMO as a distinct disease, which required the presence of optic neuritis and myelitis for diagnosis." (PMID 25888897, 2015). "NMO is characterized by recurrent episodes of myelitis and optic neuritis and most patients have a unique antibody against NMO IgG/ AQP4." (PMID 25291981, 2014). "Anti-Aqp-4 IgG has been found to be a highly specific marker for the NMO spectrum disorders that include classic NMO, isolated optic neuritis, isolated LETM, and isolated brain stem encephalitis." (PMID 25169022, 2014). "Compared with MOG-Ab positive and double negative (AQP4-Ab negative and MOG-Ab negative) optic neuritis, patients with AQP4-Ab positive optic neuritis are more likely to have poor visual acuity after acute phase treatment." (PMID 39470886, 2025). "Signs prompting MOGAD antibody testing, where known, were most commonly negative serology for AQP-4 antibodies [165/268 (61.6%)], detection of longitudinally extensive myelitis [126/268 (47.0%)] and bilateral optic neuritis [116/268 (43.3%)]." (PMID 40696221, 2025). "While one core clinical criterion is required for cases with evidence of AQP4-IgG, two core criteria are required for cases without the specific antibodies (seronegative), one of which must be optic neuritis, myelitis, or area postrema syndrome." (PMID 36472724, 2024). "The autoimmune optic neuritis includes forms caused by AQP4 autoimmunity and anti-MOG-associated disease, characterized by bilateral optic neuritis, unlike MS." (PMID 38673027, 2024). "Patient 6 with anti-AQP4 antibody showed no symptoms of encephalomyelitis or optic neuritis except typical clinical symptoms of syphilis and MRI imaging findings; no serum tests were conducted." (PMID 37346161, 2023). "Notably, anti-MOG antibodies are detected in various demyelinating diseases, including AQP4-seronegative NMOSD, recurrent optic neuritis, and acute disseminated encephalomyelitis (ADEM)." (PMID 38138980, 2023). "Despite these different patterns of demyelination, MOGAD and AQP4 + NMOSD share some clinical features, such as optic neuritis and longitudinally extensive myelitis, and cytokine profiles (upregulation of Th17-related cytokines) in the CSF as autoantibody-associated CNS diseases." (PMID 37545724, 2023). "Optic neuritis with positivity to antibodies, such as anti-MOG antibodies and anti-aquaporin-4 antibodies, may have a poor visual prognosis." (PMID 38179351, 2023). "This study reveals different immunological mechanisms between AQP4-ON and MOG-ON based on transcriptomics analysis of patients’ whole blood, which may expand the current knowledge regarding optic neuritis." (PMID 36969199, 2023). "After removing patients with only optic neuritis (ON) during a recent relapse, the sNfL levels were slightly increased in the AQP4-ab+NMOSD and MOGAD groups, and the difference of sNfL levels between AQP4-ab+NMOSD and RRMS groups diminished (p = 0.133)." (PMID 33796113, 2021). "In patients without AQP-4 IgG, it requires two core clinical characteristics disseminated in space, and at least one of these must be myelitis, optic neuritis, or area postrema syndrome supported by MRI." (PMID 33011853, 2021). "Optic neuritis with AQP4-antibody negative neuromyelitis optica spectrum disorders-like syndrome was diagnosed." (PMID 34960150, 2021). "Patients with MS (n = 83) and AQP4‐IgG‐seropositive NMOSD (n = 91) with or without a history of optic neuritis, together with healthy controls (n = 34), were imaged." (PMID 33784027, 2021).
optic neuritis (continued). "We purified serum IgG from 24 serum samples from patients with NMO spectrum disorder (NMOSD), who were positive for anti‐AQP4 antibodies (longitudinally extensive transverse myelitis [LETM], n = 14; optic neuritis [ON], n = 6; other phenotype, n = 4) and nine healthy controls." (PMID 31568704, 2019). "NMOsd includes limited forms of the disease (optic neuritis without myelitis and transverse myelitis without optic neuritis) and other less frequent clinical conditions whose lesions settle in areas of the CNS with high expression of AQP4." (PMID 31752329, 2019). "The reported characteristics of CRION (optic neuritis, dependency on steroids, and the absence of AQP4-Ab) are similar to those described in patients with MOG-IgG disease." (PMID 30382857, 2018). "Subsequent studies in AQP4-abspositive NMOSD patients demonstrated foveal thinning irrespective of optic neuritis [75▪], even in different ethnic groups [75▪,76▪,77]." (PMID 29465432, 2018). "We believe that such findings provide new insights into the understanding of the neuronal degeneration process of optic neuritis with and without AQP4 Ab." (PMID 28199381, 2017). "MOG-IgG was present in 38% of patients with long myelitis and optic neuritis who do not have AQP4 IgG." (PMID 28840314, 2017). "The frequency of AQP4, glycine receptor alpha 1 subunit, and MOG antibodies was determined in a cohort of patients with isolated optic neuritis; the combination was found in 45% (23 of 51) of the cases of the cases and was associated with unilateral or bilateral, severe or recurrent optic neuritis." (PMID 29064441, 2017). "There are no reports to our knowledge of retinal abnormalities in NMO without a history of optic neuritis, making it difficult to resolve primary vs. secondary AQP4-IgG-induced retinal injury in human NMO." (PMID 27765056, 2016). "According to this study, AQP4-IgG seronegative patients with LETM neither experience another attack of LETM nor did they develop optic neuritis." (PMID 26950113, 2016). "We found that exposure of retinal Müller cells to AQP4-IgG can produce primary retinal pathology in the absence of NMO optic neuritis." (PMID 27765056, 2016). "Aquaporin-4 antibodies (AQP4-Ab) are present in about 80 % of NMO patients and in a subset of patients with isolated longitudinally extensive myelitis or isolated optic neuritis, who are then considered to have formes frustes of NMO." (PMID 25957640, 2015). "Furthermore, both MvD+ and MvD- groups were comprised of comparable proportions of MS, anti-AQP4 antibody and anti-MOG antibody-positive optic neuritis as well as recurrences, and we believe that if the difference in etiology had any effect, they would have canceled out and resulted in minimal bias." (PMID 37104301, 2023). "Patients with optic neuropathy have three clinically validated and specific autoantibodies, binding to aquaporin 4, myelin oligodendrocyte glycoprotein (MOG), and collapsin response mediator protein 5 (CRMP5), which are considered helpful in diagnosing and classifying optic neuritis." (PMID 37448746, 2023). "Patients with AQP4-IgG could also present with partial forms of isolated myelitis or optic neuritis that did not meet the former NMO criteria." (PMID 35785363, 2022). "Notably, MOG-IgG antibodies are of great importance in NMOSD: in one study, 40% of individuals presenting with optic neuritis and transverse myelitis who were negative for AQP4-antibodies were found to be positive for MOG-IgG." (PMID 32671002, 2020). "For the longest time, retinal changes observed in AQP4-abspositive NMOSD patients, that is the thinning of the retinal nerve fiber layer (RNFL) and the formation of cysts in the inner nuclear layer (INL), were considered a result of secondary retrograde degeneration after optic neuritis." (PMID 29465432, 2018).
optic neuritis (continued). "The lack of typical LETM or clear optic neuritis and negative AQP4-Ab together with the suboptimal response to treatment with interferon-beta and fingolimod may never have led to consideration of NMOSD, as this is also seen in MS." (PMID 30319524, 2018). "Nevertheless, the patient with the highest EDSS score of 9.5 had a total of seven relapses with recurrent optic neuritis and long-segment transverse myelitis, a poor response to both high-dose corticosteroid and plasma exchange, and was negative for both the anti-AQP4 antibody and CSF OCB." (PMID 28203460, 2017). "In the six anti-flotillin-1/2-positive patients in whom the antibody was found prospectively and for whom we could evaluate medical records, testing for anti-AQP4 and anti-MOG was initially requested based on clinically assessed NMOSD core characteristics like myelitis and/or optic neuritis." (PMID 28645295, 2017). "With the detection of AQP4 antibodies, the clinical spectrum of NMO has broadened, and currently also AQP4-positive longitudinally extensive transverse myelitis (LETM) and AQP4-positive recurrent optic neuritis are regarded as part of NMO spectrum disorders (NMOSDs)." (PMID 22135746, 2011). "Diagnosis for NMOSD without AQP4-IgG is met with two core clinical characteristics, one of them being optic neuritis, acute myelitis with longitudinally extensive transverse myelitis lesions, or area postrema syndrome with dissemination in space as well as the absence of a positive AQP4-IgG test." (PMID 36579590, 2022). "However, in our cohort, the criteria still seem to have some limitations, as follows: 1) Fifty patients with LETM (25% of our demyelinating cohort) and thirteen patients with bilateral simultaneous or recurrent optic neuritis (7% of our demyelinating cohort) did not have AQP4-Ab." (PMID 24779645, 2014). "Our large single-site study of nearly 400 AQP4-NMOSD and MOGAD patients showed no adverse effect of coexisting AID on recovery from the onset attack, first optic neuritis, or time to first relapse." (PMID 40495001, 2025). "Although our patient did not present optic neuritis or transverse myelitis, it would be beneficial to consider running tests for anti-MOG-IgG and serum AQP4 antibodies, which are potentially compatible with MOG-IgG-mediated disease or NMOSD." (PMID 40729267, 2024). "One patient with HAM/TSP developed optic neuritis in addition to subacute LETM; this patient was AQP4-Ab negative as well." (PMID 22808032, 2012). "Similarly, Jarius and colleagues in 201630 reported that relapses occurred in 93% of anti-MOG positive anti-AQP4 negative NMOSD patients with disease duration ≥ 8 years and that 88% of the relapses were in the form of optic neuritis." (PMID 39789036, 2025). "This CSF profile, characterized by elevated protein with normal cell counts and negative oligoclonal bands, in the context of sequential optic neuritis and clinically evident but MRI-negative myelopathy, was felt to be more supportive of MOGAD than MS or AQP4-positive NMOSD." (PMID 41583138, 2025). "The study found that 10–27% of patients with NMO had negative serum AQP4-IgG, but a large proportion (42%) of these patients with negative serum AQP4-IgG could detect MOG antibodies, especially in patients with recurrent optic neuritis." (PMID 36385950, 2022). "MOGAD has been described to manifest with various clinical manifestations including optic neuritis, acute myelitis, NMOSD-like phenotype without AQP4 antibodies, ADEM, MDEM, cortical encephalitis, and, extremely rare, tumefactive-like presentation of demyelination lesions." (PMID 35418930, 2022). "The diagnosis of NMOSD should not be limited to seronegative or positive AQP4 antibody in a patient presenting with optic neuritis and could still be anti-MOG optic neuritis." (PMID 34484845, 2021).
optic neuritis (continued). "Partially similar to our results, a study conducted on 42 Algerian patients with optic neuritis and/or myelitis by Bouzar and colleagues in 201720 revealed that 7.1% (3/42) of their patients were positive for anti-MOG antibodies and negative for anti-AQP4 antibodies." (PMID 39789036, 2025). "However, patients with optic neuritis and/or myelitis with non-organ specific antibodies (e.g., ANA) in serum, but without recognized systemic autoimmune disorder, tend to have NMO or NMOsd rather than “lupus myelitis” or “Sjogren-related myelopathy”, regardless of AQP4-IgG serological status." (PMID 26950113, 2016).